SLPI (secretory leukocyte peptidase inhibitor)
Diseases named in the same sentence as SLPI in open-access papers (continued):
Sharing a sentence is not in itself a finding about the gene and the disease.
diabetic kidney disease (2 papers, 2024). Progressive kidney disorder caused by vascular damage to the glomerular capillaries, in patients with diabetes mellitus. "Secretory leukocyte protease inhibitor (SLPI), a protein with broad anti-inflammatory and immunoregulatory functions, its expression had altered in diabetic nephropathy (DN), likely linked to its role in reducing inflammation and protecting the kidneys from damage." (PMID 39759507, 2024). "Secretory leukocyte protease inhibitor (SLPI) is a multifunctional protein involved in the chronic inflammatory process, implicated in the pathogenesis of diabetic kidney disease (DKD)." (PMID 38501106, 2024).
dyslipidemia (2 papers, 2023 to 2024). "Third, additional experiments are warranted to validate dyslipidemia as the link between AP and T2DM and to investigate the mechanisms of SLPI and ARHGEF9 in AP and T2DM and their relationship with dyslipidemia." (PMID 39634181, 2024).
emphysema (2 papers, 2015 to 2020). "The same group also revealed that secretory leukoprotease inhibitor (SLPI) levels were significantly suppressed in Nrf2 knock-out mice, whereas the SLPI gene was highly inducible in the lungs of wild-type mice after porcine pancreatic elastase induced emphysema." (PMID 33238435, 2020).
endometrial cancer (2 papers, 2008 to 2023). Primary or metastatic malignant neoplasm involving the endometrium (mucous membrane that lines the endometrial cavity). "In this regard, a recent study from our laboratories demonstrated the progesterone-dependent co-recruitment of KLF9 and the progesterone receptor to the SLPI promoter, concomitant with induction of this gene's expression, in Ishikawa endometrial cancer cells." (PMID 18783612, 2008).
endometritis (2 papers, 2009 to 2024). An acute or chronic, usually bacterial infectious process affecting the endometrium. "In the equine endometrium SLPI mRNA expression varies depending on gestational stages, and there is an upregulation of SLPI in endometrial biopsies after experimentally induced endometritis." (PMID 38736885, 2024). "SLPI is an inhibitor of neutrophil elastase and its dramatic upregulation thus indicates that control of elastase activity is an important feature of the uterine infection." (PMID 19956711, 2009).
endophthalmitis (2 papers, 2007 to 2009). An infectious process affecting the internal structures of the eye. "In S. aureus endophthalmitis eyes, there was strong immunostaining for SLPI in the retina and vitreous with associated neutrophilic infiltrates." (PMID 18274645, 2007). "This study is the first to document that SLPI is strongly expressed in inflamed eyes in an animal model of endophthalmitis and that SLPI expression is directly associated with infiltration by inflammatorycells in ocular tissues." (PMID 18274645, 2007). "Recent studiesdemonstrate that macrophages secrete SLPI in response to bacterial lipopolysaccharides and toxins; therefore, we assume that SLPI modulates the ocular immune response in endophthalmitis." (PMID 18274645, 2007). "We used a murine model to elucidate the role of SLPI, an antimicrobial peptide, in endophthalmitis." (PMID 18274645, 2007).
head and neck squamous cell carcinoma (2 papers, 2013 to 2022). A squamous cell carcinoma that arises from any of the following anatomic sites: lip and oral cavity, nasal cavity, paranasal sinuses, pharynx, larynx, and salivary glands. "However, SLPI exhibits low expression in head and neck squamous cell carcinoma compared to other carcinomas and is associated with a better prognosis." (PMID 36588538, 2022). "We previously demonstrated that secretory leukocyte protease inhibitor (SLPI) is significantly associated with head and neck squamous cell carcinoma (HNSCC)." (PMID 23467841, 2013). "We previously showed that secretory leukocyte protease inhibitor (SLPI) gene and protein expression is significantly lower in metastatic versus non-metastatic head and neck squamous cell carcinoma (HNSCC)." (PMID 23467841, 2013).
Hepatic fibrosis (2 papers, 2017 to 2019). The presence of excessive fibrous connective tissue in the liver. "Furthermore, both TIMP1 and SLPI are induced by IL-6 as shown by studies on the pathogenesis of liver fibrosis and inflammation caused by innate immunity." (PMID 31404090, 2019).
hepatocellular carcinoma (2 papers, 2022 to 2026). A malignant tumor that arises from hepatocytes. "Conversely, SLPI is notably downregulated in hepatocellular carcinoma, suggesting its potential utility in distinguishing CCA from HCC." (PMID 41557653, 2026). "The results in this chapter indicated that SLPI appeared to modulate malignant biological behaviors of hepatoma cells and HCC progression via ERK/JNK/p38 signaling pathway." (PMID 34975323, 2022). "With the consideration of these, we here hypothesized that SLPI may affect the progression of HCC via regulating apoptosis of hepatoma cells." (PMID 34975323, 2022). "Mechanistic studies demonstrated that SLPI played a protective role in HCC progression via activating endoplasmic reticulum stress (ER stress)-mediated apoptosis of hepatoma cells, which could be regulated by MAPK signaling pathways." (PMID 34975323, 2022).
inflammatory breast carcinoma (2 papers, 2015 to 2022). An advanced, invasive breast adenocarcinoma characterized by the presence of distinct changes in the overlying skin. "It is also revealed SLPI is overexpressed in rarely developed inflammatory breast cancer with highly angiogenic and metastatic capacity." (PMID 25954138, 2015).
influenza infection (2 papers, 2012 to 2022). "To demonstrate that SLPI has the ability to protect airway epithelium from influenza infection by inhibiting proteolytic cleavage, we incubated various amounts of recombinant human SLPI (rhSLPI) to our traditional viral titer assay." (PMID 22496898, 2012). "It is worthy to note that we show a direct inverse relationship between the levels of secreted SLPI and secreted protease expression, suggesting a potential novel antiviral mechanism by which EGCG could be protective against influenza infections." (PMID 22496898, 2012).
keratitis (2 papers, 2009 to 2017). A corneal disease that is characterized by inflammation of the cornea. "We used a murine model to help elucidate the role of SLPI, an antimicrobial peptide, in inflammatory and infectious keratitis." (PMID 20309414, 2009). "In conjunction with our findings, SLPI likely plays a similarly important pathophysiologic role in S. aureus keratitis." (PMID 20309414, 2009). "There was intense staining of SLPI localized in the eye structures compromised by inflammation; positive staining for SLPI in the corneal epithelium and stroma corroborated the slit lamp findings of keratitis." (PMID 20309414, 2009). "The broad-spectrum antimicrobial activity of PI3 and SLPI proteins have led to investigation into their potential as treatments for infectious diseases, and could therefore be explored as adjunct antimicrobials for keratitis." (PMID 28573109, 2017). "To determine whether SLPI has a role in primary infectious keratitis, a condition in which SLPI has not been described, we investigated and quantified SLPI expression in infected and noninfected corneas using a murine model." (PMID 20309414, 2009).
lung disease (2 papers, 2008 to 2011). "Secretory leukoproteinase inhibitor (SLPI) is an important inhibitor of neutrophil elastase (NE), a proteinase implicated in the pathogenesis of lung diseases such as COPD." (PMID 18699987, 2008). "Cathepsins may also exacerbate lung disease by weakening the host defenses by breaking down and inactivating SLPI (secretory leukocyte protease inhibitor), beta-defensins 2 and 3 (HBD-2 and HBD-3), and lactoferrin." (PMID 21980493, 2011).
melanoma (2 papers, 2011 to 2021). A malignant, usually aggressive tumor composed of atypical, neoplastic melanocytes. "In melanoma progression, SLPI is functionally related to kallikreins, which is an important signature in intercellular adhesion, keratinocyte differentiation, and cell exfoliation." (PMID 33511023, 2021). "Some of these genes had already been described in earlier studies as being down-regulated during melanoma progression: COL17A1, DSC3, KLK7, SLPI and KLK8, or over-expressed, e.g. CCL20, THBS1 and THBS4." (PMID 22032772, 2011).
oral squamous cell carcinoma (2 papers, 2021 to 2022). "Specifically, in vitro, SLPI was inversely associated with tumor progression and invasion of oral squamous cell carcinoma; and in tumor specimens, gene and protein levels of SLPI were lower in metastatic HNC compared to non-metastatic HNC." (PMID 34214131, 2021).
osteoarthritis (2 papers, 2021 to 2025). A noninflammatory degenerative joint disease occurring chiefly in older persons, characterized by degeneration of the articular cartilage, hypertrophy of bone at the margins and changes in the synovial membrane. "Secretory Leukocyte Protease Inhibitor (SLPI) has emerged as a key endogenous regulator of inflammation, protease activity, and immune responses—hallmarks of osteoarthritis (OA) pathophysiology." (PMID 40723781, 2025). "Secretory Leukocyte Protease Inhibitor (SLPI) has emerged as a multifaceted modulator in osteoarthritis (OA), acting through anti-inflammatory, anti-protease, chondroprotective, and immunomodulatory pathways." (PMID 40723781, 2025). "While SLPI is best known for its anti-inflammatory and antimicrobial roles, increasing evidence suggests that it also participates in bone metabolism and may influence the pathophysiology of degenerative joint diseases, such as osteoarthritis (OA)." (PMID 40723781, 2025). "In addition, the comparison between our data and osteoblasts from mice cultured in vitro revealed that several genes (e.g., SLPI, MARCKS, CPE etc.), which are not correlated with osteoarthritis pathogenesis, show fundamental differences of expression levels between human and mouse osteoblasts." (PMID 34428745, 2021).
papillary thyroid cancer (2 papers, 2017 to 2018). "For example, patients with papillary thyroid cancer have high-concentrations of SERPINE2 and SLPI (secretory leukocyte protease inhibitor)." (PMID 29632742, 2018). "The aim of this study was to assess serum SERPINE2 and SLPI concentrations in a group of 36 patients with papillary thyroid cancer (PTC) and a group of 19 subjects with multinodular nontoxic goiter (MNG)." (PMID 28255192, 2017).
renal fibrosis (2 papers, 2019 to 2023). A final common manifestation of a wide variety of chronic kidney diseases characterized by glomerulosclerosis and tubulointerstitial fibrosis. "Similarly, the urinary levels of PLTP and SLPI are both increased in CKD patients with renal fibrosis." (PMID 38027143, 2023).
sarcoidosis (2 papers, 2022 to 2024). Sarcoidosis is a multisystemic disorder of unknown cause characterized by the formation of immune granulomas in involved organs. "When we classified patients according to disease etiology, higher SLPI levels were found in Sarcoidosis than in other etiologies, and levels of lysozyme were similar in all groups." (PMID 38673881, 2024). "The levels of AMPs in the PBAL samples were significantly lower in sarcoidosis compared to controls for SLPI (p < 0.01) and hBD-1 (p < 0.01)." (PMID 36258251, 2022). "The lower airways levels of the antimicrobial peptides SLPI and hBD-1 also differed between sarcoidosis and controls, with lower levels in sarcoidosis." (PMID 36258251, 2022). "Interestingly, we found significantly lower values for SLPI and hBD-1 in our study for sarcoidosis patients compared to controls." (PMID 36258251, 2022).
airway hyperresponsiveness (1 paper, 2024). "In addition, it has been reported that SLPI inhibits airway hyperresponsiveness through IL-17A regulation." (PMID 38673881, 2024).
Alzheimer disease (1 paper, 2023). A progressive, neurodegenerative disease characterized by loss of function and death of nerve cells in several areas of the brain leading to loss of cognitive function such as memory and language. "Thus, in the analysis of the Mayo RNA-Seq dataset for Alzheimer’s disease, four of the DV genes detected in the control vs. AD comparison that have the largest estimated SD ratio above 1 are LTBP2, SLPI, C2orf40, and SLC47A1." (PMID 37790621, 2023).
benign tumors of the thyroid gland (1 paper, 2017). "Our findings indicate that the estimation of SERPINE2 and SLPI serum concentration may allow the preoperative differentiation of malignant and benign tumors of the thyroid gland." (PMID 28255192, 2017).
breast tumors (1 paper, 2014). "Additionally higher levels of SLPI were also observed in 4T1.2 breast tumors in vivo following immunohistochemical staining." (PMID 25110884, 2014).
carotid atherosclerosis (1 paper, 2017). A thickening and loss of elasticity of the walls of carotid arteries that occur with formation of atherosclerotic plaques. "The downregulation of genes for secretory leukocyte peptidase inhibitor (SLPI), uncharacterized LOC730101, and growth arrest specific 6 (GAS6) in carotid atherosclerosis associated with the symptoms of cerebral embolization in both datasets included in this study was also demonstrated." (PMID 28659610, 2017). "The role of SLPI and LOC730101 in human carotid atherosclerosis is largely unknown." (PMID 28659610, 2017).
cervical dysplasia (1 paper, 2021). "SLPI and PPL exhibited a drastic shift in their expression patterns from cervical dysplasia to cancer, expressing at low levels." (PMID 34944802, 2021). "Five out of ten consistently upregulated genes (CEBPD, KRT16, SLPI, RPS29, and PPL) were also increased in cervical dysplasia." (PMID 34944802, 2021). "Unlike CEBPD, SLPI, KRT16, and RPS29, NOTCH1 expression in these cell lines did not match the increase seen in cervical dysplasia and cancer samples in silico." (PMID 34944802, 2021).
cholangiocarcinoma (1 paper, 2026). A carcinoma that arises from the intrahepatic biliary tree (intrahepatic cholangiocarcinoma) or from the junction, or adjacent to the junction, of the right and left hepatic ducts (hilar cholangiocarcinoma). "Our findings revealed that SLPI is significantly upregulated in human cholangiocarcinoma (CCA) tissues, hamster CCA models, and CCA cell lines." (PMID 41557653, 2026). "Nevertheless, direct evaluation of SLPI-targeted interventions was beyond the scope of the present work, and future studies will be required to determine whether SLPI inhibition can be safely and effectively exploited for therapeutic benefit in cholangiocarcinoma." (PMID 41557653, 2026). "Importantly, SLPI may function as a molecular bridge linking inflammation-driven signaling to vasculogenic mimicry (VM) in cholangiocarcinoma." (PMID 41557653, 2026).
chronic kidney disease (1 paper, 2025). Impairment of the renal function secondary to chronic kidney damage persisting for three or more months. "Furthermore, the antifibrotic properties of SLPI underscore its therapeutic potential in halting AKI progression to chronic kidney disease." (PMID 41373782, 2025).
chronic lung disease (1 paper, 2024). According to the definitions of the American and British Thoracic Societies, including pulmonary functional tests, X-rays, and CT scans for items such as fibrosis, bronchiectasis, bullae, emphysema, nodular or lymphomatous abnormalities. "In this study, the role of SLPI in the pathogenesis of chronic lung disease was evaluated in ENaC-Tg mice – a model of muco-obstructive pulmonary disorders." (PMID 39301022, 2024). "In the present study, we aimed to elucidate the role of SLPI in chronic lung disease." (PMID 39301022, 2024).
cyst (1 paper, 2014). A sac-like closed membranous structure that may be empty or contain fluid or amorphous material. "The consequent upregulation of SLPI, SPRR2, and EPGN could then contribute to cyst formation in the skin of MADISH patients by the observed interference with stratum corneum desquamation and epidermal barrier formation." (PMID 24503019, 2014). "Indeed, we found strong expression of NQO1, SLPI, SPRR2, and EPGN in the affected epidermis and cyst epithelium of these patients." (PMID 24503019, 2014). "Indeed, we detected strong expression of SPRR2, SLPI, EPGN and of the classical NRF2 target NQO1 in the epidermis and cyst epithelium of MADISH patients, with particularly strong staining of SPRR2, SLPI, and NQO1 in differentiated keratinocytes." (PMID 24503019, 2014).
desminopathies (1 paper, 2023). "and the results were validated using ROC curves to obtain three genes, including desminopathies (DES), beta-globin gene (HBB), and secretory leukocyte protease inhibitor (SLPI)." (PMID 37070095, 2023).
experimental autoimmune encephalomyelitis (1 paper, 2012). An autoimmune demyelinating disease of the central nervous system that is produced experimentally in animals by the injection of homogenized brain or spinal cord in Freund's adjuvant. "Indeed SLPI is known to be markedly upregulated in a rat model of the disease called experimental autoimmune encephalomyelitis." (PMID 22436018, 2012).
frontotemporal lobar degeneration (1 paper, 2023). "Then, the secretory leukocyte protease inhibitor protein(SLPI) is known to regulate the penetrance of frontotemporal lobar degeneration (FTLD) in patients who have mutations in the progranulin gene." (PMID 37790621, 2023).
fungal infections (1 paper, 2018). "Besides, the expression of SLPI gene responsible for resistance to viral, bacterial and fungal infections is down-regulated in the muscle samples of elderly individuals." (PMID 30050560, 2018).
gastritis (1 paper, 2011). Inflammation of the stomach. "Mucosal levels of Secretory Leukocyte Protease Inhibitor (SLPI) are specifically reduced in relation to H. pylori-induced gastritis." (PMID 21612671, 2011). "In contrast to other diseases, SLPI seems not to have a regulatory role for Progranulin in H. pylori-mediated gastritis." (PMID 21612671, 2011). "Considering the central role of the elastase/SLPI equilibrium for the conversion of Progranulin to granulins and the previously identified deregulation of elastase/SLPI expression in H. pylori-induced gastritis, we anticipated a negative correlation between SLPI and Progranulin for this disease." (PMID 21612671, 2011).
gonococcal infection (1 paper, 2020). "Here, we show that gonococcal infection of human macrophages led to significant reduction in host defense CAMP genes expression encoding LL-37, HBD-1 and SLPI." (PMID 32085531, 2020). "The data demonstrated that gonococcal infection led to significant reduction in the expression of LL-37, HBD1 and SLPI compared to uninfected cells using quantitative RT-PCR." (PMID 32085531, 2020).
human papilloma virus infection (1 paper, 2022). An infectious process caused by a human papillomavirus. "The blocking of the annexin A2 heterotetramer by SLPI inhibits the human papilloma virus infection." (PMID 36012891, 2022).
ischemic heart disease (1 paper, 2022). "Overexpression of the protease inhibitor using cardiac-selective overexpression of SLPI was shown to be a novel modality and be fundamental evidence for alternative therapeutic strategy for ischemic heart disease." (PMID 36061560, 2022).
ischemic stroke (1 paper, 2020). A stroke disorder caused by obstruction of blood flow to the brain, due to thrombotic (local blood clot formation) or embolic (due to a blood clot or other material traveling from another site) event. "These included genes that have been previously associated with CVD in human studies such as PTX3 (pentraxin 3) and S100A12 (EN-RAGE), as well as genes that have been associated with CVD only in animal studies such as ANXA3 and SLPI, both shown to be up-regulated in rodent models of ischemic stroke." (PMID 32780732, 2020).